FTO (FTO alpha-ketoglutarate dependent dioxygenase)
Diseases named in the same sentence as FTO in open-access papers (continued):
Sharing a sentence is not in itself a finding about the gene and the disease.
breast cancer (continued). "FTO can up-regulate PPARγ expression, enhance adipogenesis, and thus promote the proliferation of breast cancer cells." (PMID 38560499, 2024). "GAS5 regulated by FTO-mediated m6A modification represses the growth of breast cancer via the IGF2BP2/QKI pathway, suggesting that the FTO/GAS5/IGF2BP2/QKI pathway can be a potential target for breast cancer treatment." (PMID 38782769, 2024). "One on hand, FTO promotes breast cancer cell proliferation, colony formation, cellular invasion, and metastasis in vitro and in vivo." (PMID 38545841, 2024). "FTO plays an important regulatory role in acute myeloid leukemia, breast cancer, melanoma, lung cancer and GC." (PMID 38200441, 2024). "The present study aimed to evaluate the risk of FTO polymorphisms rs9939609, rs1477196, and rs9930506; analyze the methylation status of FTO promoters among Mexican women with breast cancer (BC); and investigate by in silico analysis the methylation status in the region near these polymorphisms." (PMID 39040764, 2024). "The compound 18,077 and 18,097, two selective inhibitors of FTO, can inhibit the cell cycle process of breast cancer." (PMID 38560499, 2024). "FTO is involved in chemotherapy resistance in various tumor types, including colorectal cancer, breast cancer, acute myeloid leukemia, gastric cancer, and glioblastoma." (PMID 39295930, 2024). "Consistent with previous reports, we showed that FTO expression was relatively higher in breast cancer tissues and cells." (PMID 38782769, 2024). "Recent studies have revealed that FTO, an important molecule involved in m6A modification, is closely involved in a variety of tumors including breast cancer." (PMID 38782769, 2024). "In the present study, we found that the expression of lncRNA GAS5 was decreased in breast cancer and regulated by FTO-mediated m6A modification." (PMID 38782769, 2024). "Recent studies have found that FTO is involved in the occurrence and development of various cancer, such as breast cancer, endometrial cancer, thyroid cancer, colorectal cancer and pancreatic cancer." (PMID 38200441, 2024). "Mechanism studies showed that exosomal piRNA-17560 enhanced its stability by binding to 3′UTR of FTO mRNA in breast cancer cells, thereby promoting the expression of FTO." (PMID 38302430, 2024). "LncRNA GAS5 expression decreased in breast cancer and was regulated by FTO-mediated m6A modification in an IGF2BP2-dependent manner, resulting in decreased GAS5 stability and expression." (PMID 38782769, 2024). "Examples include the METTL3 inhibitor STM2457 in AML and cervical cancer, as well as CS1 and CS2 in AML and the FTO inhibitor 18097 in breast cancer." (PMID 39726589, 2024). "We also demonstrated that the mechanism of FTO in OA involves different tissues, including blood, thyroid, liver, bladder, and breast cancer." (PMID 39363112, 2024). "Recent studies suggested that FTO, an important molecule involved in m6A modification, is closely involved in a variety of tumors including breast cancer." (PMID 38782769, 2024). "The upstream regulator STAT3 promotes FTO expression in breast cancer, resulting in doxorubicin resistance that can be reversed by FTO knockdown." (PMID 38545841, 2024). "In breast cancer cells, over expression of FTO gene promotes glycolysis and modulators of PI3K/AKT signal transduction pathway." (PMID 37471425, 2023). "In early-stage breast cancer (I + II), the combination of FTO, PIK3CB, CEA and CA153 yielded an AUC of 0.895, sensitivity of 77.22% and specificity of 85.71%." (PMID 37861518, 2023). "The diagnostic value of FTO, PIK3CB, CEA and CA15-3 in breast cancer was evaluated by constructing ROC curves." (PMID 37861518, 2023). "For example, m6A modification can regulate the malignancy of breast cancer lung metastasis cells, and overexpression of FTO can significantly inhibit the lung colonization of BT-549LMF3 cells." (PMID 38094306, 2023).
breast cancer (continued). "Rhein, competitively bounds to FTO or AlkB catalytic in vitro, displayed the enhancement of antiproliferative effects of atezolizumab based on breast cancer (4T1) regression." (PMID 37063421, 2023). "Studies have shown that m6A “eraser” FTO is significantly up-regulated in breast cancer, which can promote breast cancer cell proliferation, colony formation and reduce apoptosis." (PMID 37671941, 2023). "Then, we evaluated the diagnostic value of FTO, PIK3CB, CEA, and CA15-3 alone and in combination for breast cancer." (PMID 37861518, 2023). "Mechanistically, FTO exerted its oncogenic role in breast cancer via demethylating BCL2 Interacting Protein 3 (BNIP3), a pro-apoptosis member in the Bcl-2 apoptotic protein family." (PMID 35409166, 2022). "The inhibition of FTO by MO-I-500 reduced the proliferation of breast cancer cells, whereas the over-expression of FTO significantly promoted breast cancer progression." (PMID 35628623, 2022). "In breast cancer FTO is also overexpressed in mastectomy tissue; specifically in HER-2 high subtypes." (PMID 35409166, 2022). "To date, METTL3, ALKBH5, FTO, and YTHDF2 have been implicated in promoting breast cancer tumorigenesis by affecting cancer cell survival/proliferation and cancer stem cell pluripotency 23-26." (PMID 35966596, 2022). "BNIP3, a member of the Bcl-2 family, is a target of FTO in breast cancer that mediates cell proliferation and apoptosis." (PMID 35219326, 2022). "The oncogenic role of FTO in breast cancer was studied by comparing breast cancer cell lines to normal breast cells." (PMID 35409166, 2022). "The FTO gene is highly expressed in breast cancer, acute myeloid leukaemia (AML), and glioblastoma and promotes the progression of these cancers, and related drugs have been developed." (PMID 36389678, 2022). "Meanwhile, some studies demonstrated that FTO had oncogenic roles in breast cancer, acute myeloid myeloid leukemia and melanoma." (PMID 36302751, 2022). "Increasing data show that FTO as an m6A demethylase plays an oncogenic role in acute myeloid leukemia, breast cancer and melanoma, but restrains ovarian cancer stem cell self-renewal." (PMID 35858900, 2022). "For instance, Liu and his team showed that FTO overexpression in breast cancer cells affects energy metabolism via the PI3K/AKT signaling pathway." (PMID 35409166, 2022). "In breast cancer cells, FTO deletion induces EMT by increasing m6A levels and altering the 3′-terminal processing of key mRNAs along the Wnt signalling cascade." (PMID 36358640, 2022). "Four additional V loci were identified from looking up MD and breast cancer susceptibility SNPs in GWAS of V, including 5q23.2 (PRDM6), 8p21.2 (EBF2), 12p12.1 (SSPN), and 16q12.2 (FTO)." (PMID 36344993, 2022). "Rhein is known as the first cell-active FTO inhibitor and was demonstrated to inhibit the occurrence of breast cancer." (PMID 36553003, 2022). "Four additional loci for MD or breast cancer risk, 5q23.2 (PRDM6), 8p21.2 (EBF2), 12p12.1 (SSPN), and 16q12.2 (FTO), were also found associated with V." (PMID 36344993, 2022). "In breast cancer, FTO mediated the demethylation of m6A at the 3′-UTR of Bnip3, a pro-apoptotic gene, resulting in YTHDF2-mediated degradation of the Bnip3 transcript." (PMID 35350378, 2022). "Recently, FTO was discovered to increase the expression of ADP ribosylation factors like GTPase 5B (ARL5B) in breast cancer cells by inhibiting miR-181b-3p." (PMID 36553003, 2022). "Mechanistically, FTO overexpression in breast cancer cells increases energy metabolism via the PI3K/AKT signaling pathway, which is abnormally activated in many human cancers." (PMID 35409166, 2022). "Another study demonstrated the demethylase FTO promotes breast cancer progression by inhibiting BNIP3." (PMID 35197112, 2022). "FTO has been involved in the tumor progression of breast cancer via suppressing BCL2 interacting protein 3 in an m6A-dependent way." (PMID 34076564, 2021).
breast cancer (continued). "These breast cancer patients with distinct molecular subtypes all represented lower expression of FTO, METTL3, and METTL14, and higher expression of YTHDF1 and YTHDF3 in tumor compared to the corresponding adjacent samples." (PMID 34804948, 2021). "In breast cancer, FTO promotes cancer cell proliferation and metastasis through negative regulation of BNIP3 mRNA, and the high level of FTO is associated with the poor prognosis." (PMID 33816306, 2021). "For example, the m6A demethylase FTO promoted breast cancer progression by inhibiting BNIP313, and the HBXIP-elevated methyltransferase METTL3 promoted breast cancer progression by inhibiting the tumor suppressor let-7 g." (PMID 34151731, 2021). "In breast cancer, FTO knockdown increases the level of m6A modification in the 3′-UTR of BNIP3 mRNA and thereby increases its expression, which in turn induces cell apoptosis." (PMID 33926508, 2021). "FTO was found to play oncogenic roles in acute myeloid leukemia, melanoma, breast cancer, and cervical cancer through its posttranscriptional regulation function." (PMID 34218271, 2021). "In HER2-positive breast cancer, FTO also reinforces cell invasion and migration in vitro through the FTO/miR-181b-3p/ARL5B signalling pathway." (PMID 34044876, 2021). "The down-regulation of FTO, knockdown, the proliferation and metastasis of breast cancer tissues and cells were significantly inhibited, while the number of apoptotic cancer cells increased." (PMID 34211849, 2021). "For example, FTO can regulate the migration and invasion of breast cancer cells by regulating the FTO/Mir-181B-3P/ARL5B signaling pathway, which ultimately affects the development of breast cancer." (PMID 34660577, 2021). "In human epidermal growth factor receptor 2 (HER2)-positive breast cancer, it is reported that m6A “eraser” FTO inhibits miR-181b-3p and upregulates the expression of oncogenic ARL5B." (PMID 35004679, 2021). "Several FTO small-molecule inhibitors, including meclofenamic acid and MO-I-500 have shown effective activity to inhibit the survival and growth of GBM and breast cancer cells by inhibiting the catalytic activity of FTO." (PMID 33731118, 2021). "FTO, as a member of the AlkB family, is the first identified m6A demethylase/eraser, which maps to chromosome 16q12.2 and is highly expressed in most breast cancers." (PMID 34044876, 2021). "With the increase of malignancy of breast cancer, the expression level of several m6A RNA methylation regulators, such as FTO, HNRNPA2B1 YTHDC1, IGF2BP1, IGF2BP2 and IGF2BP3, decreased or increased." (PMID 34141492, 2021). "In this study, the expression of m6A “writers” METTL3, METTL14, and “erasers” FTO were downregulated in 112 tumor samples compared to the paired normal controls based on TCGA breast cancer dataset." (PMID 34804948, 2021). "Targeting FTO by potent inhibitors held therapeutic promise against various types of cancers, including breast cancer." (PMID 34804948, 2021). "For instance, FTO, a key m6A demethylase, is significantly overexpressed in human cervical cancer, breast cancer as well as acute myeloid leukemia and serves as an oncogenic regulator for the proliferation and migration of corresponding tumor cells." (PMID 33193582, 2020). "Aberrant expression of m6A regulators, including METTL3, METTL14, WTAP, ALKBH5, and FTO, has been identified in breast cancer, as well as their potential prognostic values." (PMID 33585234, 2020). "METTL3, METTL16, ZC3H13, YTHDC1 and FTO were expressed at a low level in breast cancer, while KIAA1429, RBM15, and YTHDF1 were expressed at a high level." (PMID 33362863, 2020). "FTO promoted breast cancer cells malignant phenotypes such as proliferation, colony formation, and metastasis." (PMID 33304380, 2020).
breast cancer (continued). "Estrogen stimulates breast cancer cell proliferation by upregulating FTO and activating PI3K/Akt signaling." (PMID 33292526, 2020). "As an m6A eraser, FTO is associated with the initiation and development of various cancers including hepatocellular carcinoma (HCC), melanoma, breast cancer and glioma." (PMID 33015074, 2020). "Next, the effects of METTL3, METTL14, and FTO on distant metastasis free survival (DMFS) of total breast cancer patients and TNBC patients were analyzed using KM-plotter on-line database, respectively." (PMID 32766145, 2020). "FTO mediates m6A demethylation in the 3’UTR of BNIP3 mRNA and induces its degradation via an YTHDF2 independent mechanism, which indicates that FTO can serve as a novel potential therapeutic target for breast cancer." (PMID 32754191, 2020). "As for cancers, there are more studies on the application of FTO inhibitors, especially in the treatment of leukemia, glioblastoma, and breast cancer." (PMID 33304380, 2020). "FTO-mediated m6A demethylation has been found to regulate the occurrence and development of many cancers such as glioblastoma and breast cancer." (PMID 32443966, 2020). "BNIP3 has an anticancer effect and is negatively correlated with the expression of the m6A demethylase FTO in breast cancer; BNIP3 can slow down the growth and metastasis of FTO-overexpressing tumors." (PMID 32547955, 2020). "In summary, we provided compelling evidence that FTO, the key m6A demethylase, was up-regulated in human breast cancer." (PMID 30922314, 2019). "We first detected the levels of the m6A modification in breast cancer, and observed that FTO was up-regulated in human breast cancer tissues." (PMID 30922314, 2019). "We also found that FTO was higher expressed in breast cancer cell lines than other cancer cell lines (GSE11612)." (PMID 30922314, 2019). "Development of specific potent FTO inhibitor is considered to be a preferable therapeutic strategy for breast cancers." (PMID 30922314, 2019). "FTO promoted breast cancer cell proliferation, colony formation and metastasis in vitro and in vivo." (PMID 30922314, 2019). "Further, we identified that BNIP3, a pro-apoptotic member of the Bcl-2 family of apoptotic proteins, was the target gene of FTO in mediating breast cancer proliferation and progression." (PMID 30922314, 2019). "Significance of FTO in breast cancer is also evident by its positive role for supporting the growth of breast cancer cells in anchorage-independence and metastasis models." (PMID 31426393, 2019). "We further showed that high expression level of FTO was significantly related to poor clinic prognosis, indicating the role of FTO in regulation of breast cancer development." (PMID 30922314, 2019). "Here, we show that FTO acted as an oncogene in breast cancer by bursting cell growth and metastasis both in vitro and in vivo." (PMID 30922314, 2019). "Stable FTO-knockdown 4 T1 cells (mouse-derived breast cancer cell line) were constructed by using FTO shRNA, and subcutaneously injected into 4-week-old female BALB/c mice." (PMID 30922314, 2019). "In our study, we systematically analyzed the key regulators of m6A modification in breast cancer, and found that over 70% breast cancer tissues were highly expressed FTO." (PMID 30922314, 2019). "Mechanistically, FTO reduced apoptosis of breast cancer cells at least partially via downregulating expression of BNIP3, a pro-apoptosis gene." (PMID 30922314, 2019). "FTO dramatically promoted breast cancer cell proliferation, colony formation and metastasis through epigenetically down-regulating BNIP3." (PMID 30922314, 2019). "BNIP3 acts as a tumor suppressor and is negatively correlated with FTO expression in clinical breast cancer patients." (PMID 30922314, 2019). "FTO promoted breast cancer cell proliferation, colony formation and metastasis by reducing BNIP3 methylation and promoting BNIP3 degradation." (PMID 31801551, 2019).
breast cancer (continued). "Taken together, our results suggest that FTO plays an important role in controlling breast cancer cell growth, colony formation and cell death." (PMID 30922314, 2019). "Consistently, FTO protein was significantly overexpressed in breast tumor tissues compared to their adjunct tissues according to the quantification of IHC results, which supported our initial observation of FTO up-regulation in breast cancer." (PMID 30922314, 2019). "IHC staining data from HPA database showed a predominant upregulation of ALKBH5 but downregulation of FTO in breast carcinoma tissues in comparison with normal breast tissues." (PMID 31632489, 2019). "The fact that FTO is expressed in human breast tissue as well as its role in nucleic acid demethylation point toward a direct effect of FTO in breast cancer." (PMID 21489227, 2011). "We also showed the presence of FTO in breast tissue and found that normal breast tissue had significantly higher FTO RNA expression compared with breast cancer tissue." (PMID 21489227, 2011). "We confirmed the presence of FTO expression by performing IHC where we found that both normal breast tissue and breast cancer tissue have a positive cytoplasmic stain for FTO." (PMID 21489227, 2011). "Similarly, lower expression levels of FTO-BTK/E2F1 also significantly enhanced OS in breast cancer patients." (PMID 41281757, 2025). "Our data showed that FTO is highly expressed in breast cancer and enhances tumorigenic activity." (PMID 41281757, 2025). "To our knowledge, several candidate FTO inhibitors have entered preclinical studies and early-phase clinical trials, and we anticipate their clinical translational potential for the treatment of breast cancer." (PMID 41269404, 2025). "FTO upregulation that increases demethylation of m6A has been associated with melanoma and causes downregulation of BNIP3, a tumor suppressor gene in breast cancer." (PMID 40722726, 2025). "Similarly, combining peripheral blood m6A modification levels with METTL14 and FTO regulatory genes achieved an AUC of 0.929 for breast cancer diagnosis, which was also better than the biomarkers CEA (0.599) and CA153 (0.572)." (PMID 40698864, 2025). "Finally, multifactorial survival analysis revealed that lower expression levels of FTO-BTK/c-Myc-E2F1 significantly improved OS in breast cancer patients." (PMID 41281757, 2025). "In addition, the apoptosis induced by FTO ablation has been reported in several cancer types including breast cancer, colorectal cancer, acute myeloid leukemia, and so on." (PMID 40712780, 2025). "Subsequently, further subtype-specific analysis revealed significantly elevated FTO expression in the three main clinical subtypes of breast cancer, compared to normal tissue, which reflects the broader trend observed across breast cancer." (PMID 41281757, 2025). "Furthermore, they showed that in breast cancer patients high FTO levels correlate with poorer survival." (PMID 40022434, 2025). "Furthermore, FTO is involved in regulating key signaling pathways, including regulating the metabolic processes of breast cancer cells through the m6A methylation modification pathway, which influences tumor growth and proliferation." (PMID 41269404, 2025). "In liver cancer and breast cancer, FTO promotes tumor progression by regulating the m6A level of oncogenes, but its role in osteosarcoma and the upstream and downstream regulatory network remains unclear." (PMID 41145484, 2025). "Next, we explored the biological functions of the FTO/GAS5/IGF2BP2/QKI axis in breast cancer." (PMID 38782769, 2024). "The expression of FTO was relatively higher in breast cancer tissues and cells." (PMID 38782769, 2024). "Additionally, FTO expression is upregulated in metabolic diseases such as cervical cancer, breast cancer, and diabetes." (PMID 38995602, 2024). "FTO overexpression enhanced the doxorubicin resistance of breast cancer cells by STAT3 pathway." (PMID 38782769, 2024).